CXCL5 (C-X-C motif chemokine ligand 5)
Diseases named in the same sentence as CXCL5 in open-access papers (continued):
Sharing a sentence is not in itself a finding about the gene and the disease.
liver cancer (13 papers, 2014 to 2025). An epithelial or non-epithelial malignant neoplasm that arises from the liver. "Several CXCL genes have been recognized to be potential markers of TAN2 phenotype, such as CXCL5, which has been reported to independently predict reduced overall survival duration and total risk of reoccurrence in liver cancer patients." (PMID 37540227, 2023). "HIF1 activates the NF-κB pathway in liver cancer cells and promotes CXCL5 secretion, further attracting tumor-associated neutrophils to liver cancer." (PMID 35659268, 2022). "Our previous work demonstrated that CXCL5 enhances liver cancer cell migration and proliferation through both autocrine and paracrine mechanisms." (PMID 41259383, 2025). "CXCL5 is known to be secreted by stroma and cancer cells and via autocrine and paracrine pathways to modulate tumorigenesis in prostate and liver cancers; however, only a few reports have discovered the function of CXCL5 in prostate stroma cells." (PMID 39765818, 2024). "CXCL5 is an important chemokine in TME, and CXCL5 overexpression is closely related to survival time, recurrence and metastasis of liver cancer patients." (PMID 36869083, 2023). "Small interfering RNA (siRNA) and recombinant protein were used to assess CXCL5 effects on the movement of liver cancer cells (LCCs)." (PMID 25011526, 2014). "ELR-CXC chemokines have been proposed as important mediators of tumorigenesis in a number of cancers and CXCL5 was also found over-expressed in many types of cancers, including liver cancer, mediating neutrophil infiltration and indicating poor prognosis." (PMID 25011526, 2014). "In liver cancer, tumor-associated neutrophils (TANs) stimulate miR-301b-3p to express, which subsequently inhibits the level of CYLD and LSAMP and upregulates chemokine (CXCL5), leading to a higher infiltration of TANs." (PMID 39525474, 2024). "Autocrine and paracrine CXCL5 may directly chemo-attract liver cancer cells and circulating leukocytes for the development of an inflammatory microenvironment." (PMID 25011526, 2014). "CXCL5 could be produced by liver cancer cells, but also by inflammatory cells (e.g. neutrophil, monocyte, macrophage) and structure cells (e.g. epithelial, endothelial, fibroblastic)." (PMID 25011526, 2014). "Our data indicates that LCCs per se may act as the producer and receptor of CXCL5 responsible for liver cancer migration and invasion." (PMID 25011526, 2014). "However, further studies about the role of CXCL5 on the recruitment of liver cancer cells are still necessary." (PMID 25011526, 2014). "CXCL5 has been identified as a crucial mediator downstream of the transcription protein sex-determining region Y-box 9 (Sox9) and since Sox9 is required for the self-renewal and tumor propagation of liver cancer stem cells (CSCs; 35); it has been characterized as a candidate CSC marker of HCC." (PMID 38252699, 2024). "Since both CXCL3 and CXCL5 signal through CXCR2, it is plausible that CXCL3 may also promote liver cancer progression via CXCR2-dependent pathways." (PMID 41259383, 2025). "Among those, CXCL5, CXCL9, CXCL10, and CXCL11 were significantly elevated in patients with early HCC according to the Barcelona Clinic Liver Cancer (BCLC) stages 0/A compared to cirrhotic controls without HCC." (PMID 36982370, 2023).
psoriasis (13 papers, 2014 to 2025). An autoimmune condition characterized by red, well-delineated plaques with silvery scales that are usually on the extensor surfaces and scalp. "Cxcl5 expression is upregulated in keratinocytes after IL-17 exposure, in association with psoriasis pathogenesis." (PMID 32235789, 2020). "Mechanistically, this psoriasis protection was mediated by IκBζ deficiency in keratinocytes abrogating the induction of specific proinflammatory target genes, including Cxcl5, Cxcl2, Csf2, and Csf3, in response to IL-17A or IL-36." (PMID 31622280, 2019). "Molecular analysis of the skin of IgG- and anti-IL36R-treated K14-IL17Aind mice revealed effective suppression of psoriasis-associated cytokines (Il36a, Il36g, Il36b, Il23a, and Tnf), chemokines (Cxcl1, Cxcl5, and Ccl2) and antimicrobial-peptides (such as Defb4) on mRNA level." (PMID 38162658, 2023). "Among others, important psoriasis-associated target genes of IκBζ include certain chemo- and cytokines (e.g., Cxcl1, Cxcl2, Cxcl5, Ccl3, and Il17c) as well as antimicrobial proteins, such as S100 calcium-binding proteins (e.g., S100a9), β-defensin-2 (Defb4), and lipocalin-2 (Lcn2)." (PMID 31622280, 2019). "The heatmaps revealed an increase in several classic proinflammatory cytokines such as Tnf, Il6, Il1a, Il23α and a small number of chemokines, including Ccl19, Ccl20, Cxcl13, and Cxcl5, which are typically elevated in psoriasis patients, in CD169+ macrophages." (PMID 38891893, 2024). "In the obese condition, CXCL5 synergized endoplasmic reticulum stress to exacerbate psoriasis symptoms." (PMID 36009523, 2022). "Furthermore, it has been demonstrated that suppression of miR-31-5p in keratinocytes in psoriasis suppresses NF-κB-driven promoter-luciferase activity and IL-1β, CXCL1, and CXCL5 production." (PMID 39259390, 2024). "RT-qPCR experiments further confirmed that CXCL16 expression was significantly elevated in MDMs from psoriasis patients compared to healthy controls, while no statistical differences were observed for CXCL1, CXCL3, and CXCL5." (PMID 40722833, 2025).
periodontitis (12 papers, 2015 to 2026). An acute or chronic inflammatory process that affects the tissues that surround and support the teeth. "In the late stages, S100a8 and S100a9, which encode damage-associated molecular patterns, and Cxcl5 and Cxcl3, which encode chemokines, are prominently upregulated, highlighting the persistent recruitment of neutrophils, a hallmark of periodontitis." (PMID 40076622, 2025). "They found significantly higher levels of circulating CXCL5 in smokers with periodontitis, which correlated with probing depth, attachment loss, and tobacco consumption." (PMID 25999952, 2015). "To confirm our findings, we analyzed the expression level of the CXCL5 gene in periodontal tissues of 12 patients with periodontitis and healthy controls using immunohistochemistry." (PMID 38168591, 2024). "The functional enrichment results showed that CXCL5 is involved in the IL-17 signaling pathway, which is closely related to the occurrence of periodontitis." (PMID 38168591, 2024). "Salicin treatment significantly inhibited the expression of CXCL1, CXCL2 and CXCL5 in the gingival tissue of WT-periodontitis mice, while these inhibitory effects of salicin were abolished in the Gnat3-/- periodontitis mice." (PMID 38605968, 2024). "Our present pilot study suggests that CXCL5 and CXCL6 have the potential to be used as a diagnostic biomarker of periodontitis." (PMID 38168591, 2024). "The results were consistent with the bioinformatics analysis, showing a significant increase in the expression level of the CXCL5 gene in patients with periodontitis." (PMID 38168591, 2024). "In this study, we found a significant correlation between the CXCL5 gene and the occurrence of periodontitis through differential expression analysis and WGCNA enrichment analysis." (PMID 38168591, 2024). "In conclusion, we found that CXCL5 and CXCL6 are closely associated with the occurrence of periodontitis." (PMID 38168591, 2024). "In conclusion, we integrated multiple bioinformatics analyses and found that CXCL5 and CXCL6 are closely associated with the occurrence of periodontitis." (PMID 38168591, 2024). "In this disorder, periodontitis has been associated with a marked upregulation of IL-17A and other related cytokines, as well as chemokines responsible for neutrophil recruitment (CXCL2, CXCL5)." (PMID 41462866, 2025). "CXCL5 was one of the most upregulated genes, while LCE2 and LCE3 were considerably downregulated T2DM-related periodontitis." (PMID 38241313, 2024). "The results of the PPI analysis indicated that CXCL5 and CXCL6 are key genes involved in the development of periodontitis." (PMID 38168591, 2024). "We compared the gene expression level using immunohistochemical, and found that the IOD/Area score of CXCL5 and CXCL6 in periodontitis patients were significantly higher than those in health controls (p < 0.01)." (PMID 38168591, 2024). "CXCL5 was among the top 15 upregulated DEGs, while LCE2 and LCE3 were among the top 15 downregulated DEGs observed in T2DM-related periodontitis." (PMID 38241313, 2024). "The expression levels of CXCL5 and CXCL6 were significantly higher in periodontitis patients compared to those in controls." (PMID 38168591, 2024). "The enrichment of TNFRSF21+ fibroblasts with high expression of CXCL1, CXCL2, CXCL5, CXCL6, CXCL13, and IL24 was detected in patients with periodontitis compared to healthy individuals." (PMID 35154475, 2022). "Currently, there is limited research on CXCL5 and CXCL6 as biomarkers for periodontitis." (PMID 38168591, 2024). "The PPI network analysis revealed that C-X-C motif chemokine ligand 5 (CXCL5) and C-X-C motif chemokine ligand 6 (CXCL6) could play an important role in the process of periodontitis." (PMID 38168591, 2024). "Further research is crucial to determine whether CXCL5 and CXCL6 can serve as predictive biomarkers for the diagnosis and treatment of periodontitis." (PMID 38168591, 2024).
periodontitis (continued). "ROC curve analysis showed that the AUROC values for CXCL5 and CXCL6 were 0.834 and 0.82, respectively, indicating that they might have excellent specificity and sensitivity for the diagnosis of periodontitis." (PMID 38168591, 2024). "Our study suggests that they might have predictive potential, and combining CXCL5 and CXCL6 with other biomarkers may enhance the ability to predict periodontitis." (PMID 38168591, 2024). "Of high relevance to carcinogenesis, an interesting study by Lappin and colleagues determined plasma concentrations of CXCL5 and IL-6 in systemically healthy subjects with or without periodontitis, and who either did or did not smoke." (PMID 25999952, 2015). "However, the relationship between CXCL5 and CXCL6 and periodontitis is not yet fully understood." (PMID 38168591, 2024).
coronary artery disease (11 papers, 2016 to 2025). "High levels of LIX/CXCL5 have been associated with coronary artery disease and postulated to be a potential biomarker and pharmacological target for this pathology." (PMID 36835011, 2023). "Like PF4 and CXCL5, PPBP has received little research attention in the context of ICH, but is considered a potential risk factor for coronary heart disease in patients with hyperlipidemia." (PMID 38271077, 2024). "CXCL5 is another key chemoattractant and activator of neutrophils., who mediates the circadian neutrophil recruitment to the lung, with higher expression in patients with coronary artery disease." (PMID 27798647, 2016). "In agreement with the higher expression level of C-X-C motif chemokine ligand 5 (CXCL5) in the blood of patients with MFS, CXCL5 showed an increased expression level in the plasma of patients with coronary artery disease." (PMID 29530068, 2018). "Research has indicated a negative relationship between coronary artery disease (CAD) severity and CXCL5 plasma levels." (PMID 37928902, 2023).
cervical cancer (10 papers, 2021 to 2026). A primary or metastatic malignant neoplasm involving the cervix. "Upregulated CXCL5 in patients with cervical cancer increases the oncogenic potential of HeLa cervical cancer cells by increasing the phosphorylation of ERK1/2 and Akt and the gene expression of CXCR2." (PMID 37373052, 2023). "Furthermore, the administration of exogenous CXCL3 or CXCL5 on cervical cancer cell lines contributes to proliferation and migration." (PMID 37626777, 2023). "The abnormal expression of CXCL5 contributes to the tumorigenicity of cervical cancer." (PMID 34174849, 2021). "In addition, CXCL5 contributes to the tumorigenicity of cervical cancer and is post-transcriptionally regulated by miR-577." (PMID 34833360, 2021). "However, the high expression of CXCL8, TNFAIP6, CXCL5 and CDA in cervical cancer tissues was associated with a poor patient prognosis." (PMID 34174849, 2021). "Moreover, using an in vivo model of cervical cancer, our research group and others have demonstrated the expression of a set of chemokine genes (Cxcl1, Cxcl2, Cxcl3, and Cxcl5) in stromal and epithelial cancer cells, revealing biological crosstalk in cervical carcinogenesis." (PMID 37626777, 2023). "Epiregulin was positively correlated with most chemokines, such as CXCL1, CXCL2, CXCL3, CXCL5, CXCL6, CXCL8, and CCL20, in most types of cancer, including cervical cancer." (PMID 37020674, 2023). "CXCL5 and its receptor CXCR2 are expressed by HeLa cells and CXCL5 is upregulated in cervical cancer tissues." (PMID 34833360, 2021). "The expression of CXCL5 and KIF2A was upregulated in various cancer tissues, including cervical cancer; additionally, the expression of RGS18 in the tissues of patients with ovarian cancer was also upregulated." (PMID 34827689, 2021). "We might suggest a negative correlation between CXCL5 and cervical cancer stage if CXCL5 from blood plasma exosomes is absorbed and secreted into the TME by tumor cells." (PMID 34827689, 2021).
cholangiocarcinoma (10 papers, 2016 to 2025). A carcinoma that arises from the intrahepatic biliary tree (intrahepatic cholangiocarcinoma) or from the junction, or adjacent to the junction, of the right and left hepatic ducts (hilar cholangiocarcinoma). "CXCL5 secreted by inflammatory lymphatic endothelial cells promotes migration, invasion, and metabolic reprogramming in cholangiocarcinoma, which further enhance the metastasis of cholangiocarcinoma." (PMID 39840048, 2024). "However, in cholangiocarcinoma, lymphatic endothelial cells secrete CXCL5, which induces EMT in the tumor cells." (PMID 37686093, 2023). "However, another study showed that CXCL5 induced mitochondrial ROS in cholangiocarcinoma cells." (PMID 39765818, 2024). "The CXCL5/CXCR2 axis promotes lymphangiogenesis, epithelial–mesenchymal transition (EMT), and matrix metalloproteinase (MMP) upregulation in cholangiocarcinoma (CCA)." (PMID 40564091, 2025). "The data revealed types of tumors express higher CXCL5 compared to related normal tissues, including pancreatic adenocarcinoma (PAAD), in cholangiocarcinoma (CHOL), colon adenocarcinoma (COAD), esophageal carcinoma (ESCA), rectum adenocarcinoma (READ) and stomach adenocarcinoma (STAD) tissues." (PMID 32201508, 2020).
inflammatory bowel disease (10 papers, 2009 to 2025). A spectrum of small and large bowel inflammatory diseases of unknown etiology. "Previous studies reported that CXCL5 was overexpressed in the intestinal epithelium in inflammatory bowel disease and also in malignant pancreatic diseases." (PMID 34194499, 2021). "CXCL5, IL_17C, and SLAMF1 are possible co‐acting pathways between Bell's palsy and inflammatory bowel disease." (PMID 40760834, 2025).
intrahepatic cholangiocarcinoma (10 papers, 2018 to 2025). A carcinoma that arises from the intrahepatic bile duct epithelium in any site of the intrahepatic biliary tree. "CXCL8 in human and Cxcl5 in mouse are key translational targets of METTL1 that facilitate its function in promoting PMN-MDSC accumulation in tumor immune microenvironment of intrahepatic cholangiocarcinoma." (PMID 40443650, 2025). "According to Zhou, S.-L, CXCL5 exacerbated intrahepatic cholangiocarcinoma (ICC) progression and metastasis by recruiting intratumoral neutrophils." (PMID 37784082, 2023). "Liu et.al recently revealed that METTL1-mediated m7G modification significantly regulates PMN-MDSCs accumulation in the immune microenvironment and intrahepatic cholangiocarcinoma progression through targeting CXCL8 in humans and Cxcl5 in mice." (PMID 39440054, 2024). "Moreover, METTL1 upregulates the expression of chemokines CXCL5 and CXCL8 in an m7A-dependent manner, leading to MDSCs accumulation and immunosuppression in HCC and intrahepatic cholangiocarcinoma (ICC)." (PMID 38902779, 2024). "In a preclinical mouse model of intrahepatic cholangiocarcinoma (ICC), PD-1 treatment simultaneously blocked METTL1 and its downstream chemokine pathway (CXCL8 in the human body and CXCL5 in the mouse body), boosting the immune response in the mice." (PMID 39155349, 2024).
nasopharyngeal carcinoma (10 papers, 2013 to 2023). A carcinoma arising from the nasopharyngeal epithelium. "High CXCL5 levels in the serum are associated with tumor progression in nasopharyngeal carcinoma, lymph nodes, and distant metastasis." (PMID 37015905, 2023). "In nasopharyngeal carcinoma, CXCL5/CXCR2 axis promoted cell migration and invasion by inducing EMT through ERK/GSK-3β/Snail signalling pathway." (PMID 36151545, 2022). "This study analyzed the clinical significance of serum CXCL5 (sCXCL5) levels of nasopharyngeal carcinoma (NPC) patients, with the goal of building a novel prognostic score model." (PMID 23469080, 2013). "In nasopharyngeal carcinoma, CXCL5 contributes to EMT by activating ERK/GSK-3β/Snail signaling." (PMID 35853880, 2022). "CXCL5 has been shown to activate ERK1/2 and PI3K/Akt signaling pathways in HCC cells by interacting with its receptor CXCR212 and activate the ERK/GSK-3β/snail signaling pathway in nasopharyngeal carcinoma cells." (PMID 32632106, 2020).